EPO (erythropoietin)
Diseases named in the same sentence as EPO in open-access papers (continued):
Sharing a sentence is not in itself a finding about the gene and the disease.
anemia (continued). "Case 1 was a 4.86 kg, 12 -year-old female miniature dachshund, who was evaluated for anemia that began 5 months ago and was treated with human recombinant erythropoietin at the private hospital without any diagnosis." (PMID 35898238, 2022). "Though early parenteral iron supplementations with erythropoietin (EPO) were found to be beneficial for the management of anaemia, especially in end-stage renal disease patients, it is not widely practiced as it is not feasible and affordable in India." (PMID 35385543, 2022). "Erythropoietin (EPO) is a glycoprotein hormone with a molecular weight of 30,400 that controls red cell production and has been used clinically for the treatment of a variety of diseases such as chronic renal failure and anaemia." (PMID 35072831, 2022). "Fifteen patients (27%) developed grade 3 anemia, typically managed with exogenous EPO administration and/or blood transfusion rather than dose reduction or drug discontinuation." (PMID 36358730, 2022). "Erythropoietin (EPO), a 34 kDa glycoprotein hormone and a member of the hematopoietic class I cytokine superfamily, is a growth hormone that stimulates neovascularization and has been used to treat several types of anemia." (PMID 36277197, 2022). "Our data show that α-Klotho administration had no beneficial effect in mice with CKD-associated anemia as it did not increase RBC numbers and hemoglobin levels, and it did not stimulate EPO secretion." (PMID 35813388, 2022). "A study reported that EPO-related anemia can occur early in patients with DKD, but usually does not occur in patients with NDKD of similar severity." (PMID 35773653, 2022). "Erythropoietin (EPO) stimulates erythropoiesis and is approved for the treatment of certain forms of anemia, but not for HUS-associated hemolytic anemia." (PMID 36211426, 2022). "Although four patients (7%) received blood transfusion and 12 patients (20%) received erythropoietin-stimulating agents, treatment-related anemia typically stabilized without intervention in most patients." (PMID 36358730, 2022). "It is possible that patients develop anemia when the kidneys do not produce sufficient erythropoietin (EPO) levels to promote erythropoiesis." (PMID 34873402, 2021). "Older age alone contributes to anemia, as evidenced by low erythropoietin levels in blood even though the older persons did not have chronic illnesses." (PMID 34682667, 2021). "The EPO response to fetal anemia was low or absent and EPO levels were significantly decreased in newborns with the most severe anemia." (PMID 33995348, 2021). "In the present study, more CKD than non-CKD patients were treated with EPO therapy because the proportion of preoperative anaemia is higher in renal patients than in patients without renal problems." (PMID 34838063, 2021). "Newborns with fetal anemia showed a non-significant trend to increase EPO as cord hemoglobin decreased, except for newborns in the lowest Hb quartile (Hb ≤ 9.0 g/dl) in whom EPO was significantly lower versus normal children." (PMID 33995348, 2021). "Anemia is also a common complication of renal disease because failing kidneys do not produce enough erythropoietin (EPO) to maintain normal levels of red blood cells, and the liver cannot fully compensate by secreting its own EPO." (PMID 34339435, 2021). "Transfusion support was required in eight patients (57%) with non-transfusion-dependent congenital anemia, and recombinant human erythropoietin (rhEPO) was safely administered in five patients (36%)." (PMID 34362222, 2021). "UCG could decrease renal fibrosis and anemia in CKD rats by regulating the transforming growth factor-β (TGF-β) and erythropoietin signaling pathways." (PMID 34678995, 2021). "Erythropoietin (EPO), a secreted cytokine, is FDA-approved for the treatment of anemia." (PMID 34070383, 2021).
anemia (continued). "This is already the case in a related illness, chronic kidney disease, where one of the early complications is anemia due to lack of EPO production by kidney interstitial fibroblasts-like cells." (PMID 34447792, 2021). "In human chronic cadmium intoxication (e.g., Itai-itai disease), EPO is not up-regulated as expected given severe anemia." (PMID 33429420, 2021). "It increases the erythropoietin concentrations to within the physiological range in the kidneys and liver, which increases or maintains the hemoglobin concentration in patients with CKD and anemia." (PMID 34307403, 2021). "Gut dysbiosis, nutritional imbalance (malnutrition) with dysgeusia and, most importantly, ID with or without renal dysfunction capable of reduced erythropoietin-mediated erythropoiesis, are responsible for anaemia in CHF patients." (PMID 33467658, 2021). "First, the retrospective cohort did not include several anemia biomarkers, including circulating EPO levels, vitamin B12, serum folate and haptoglobin." (PMID 34831360, 2021). "In our patients, serum EPO levels were not available, as EPO determinations are not part of any clinical laboratory routine, but an assumption of diminished levels would perfectly fit with their documented anemia prior to EPO treatment." (PMID 34565332, 2021). "Transfusion support was required in 57% of the patients with non-transfusion-dependent anemia, and recombinant human erythropoietin was safely administered in one third of the patients." (PMID 34362222, 2021). "The lack of endogenous EPO response in the groups under study favors the pharmacological administration of EPO as an adjuvant to prevent anemia in ARDS and COVID-19, thereby delaying the need for blood transfusion." (PMID 34573092, 2021). "Although recombinant EPO is effective to improve anemia, no reliable REP cell lines limit further progress of research and development of novel treatment." (PMID 34724959, 2021). "Anemia as a common metabolic complication of CKD can result in low HbA1c, which may be related to decreased erythropoietin synthesis and shortened red blood cell lifespan because of impaired renal function." (PMID 34022855, 2021). "In agreement with previous RCTs showing a safe profile of ESA in cardiac surgery, the two recent studies on anemia treatment in cardiac surgery by Ranucci and Spahn did not report an excess of thrombotic events with erythropoietin." (PMID 34205971, 2021). "Currently, the cornerstone of the therapy of anaemia is iron supplementation, with or without erythropoietin for the stimulation of haematopoiesis." (PMID 33467658, 2021). "Anemia is managed with red blood cell transfusions and erythropoiesis-stimulating agents (ESA), with a 60% response rate, particularly in patients with low endogenous erythropoietin (EPO) levels." (PMID 33401595, 2021). "Despite EPO and hepcidin playing a significant role in the development of anaemia in patients with CKD, only two studies identified in this SLR assessed the role of EPO as a risk factor for anaemia and no studies included hepcidin." (PMID 32665863, 2020). "Large studies have shown that attempts to correct anemia by erythropoietin did increase the hemoglobin value but did not lead to improved oncological outcomes in HNSCC patients undergoing radiotherapy." (PMID 32604773, 2020). "To first test the effects of anemia on colonization and T4SS function, we gavaged H. pylori into EPO−/− mice bearing a homozygous disruption in the 5′ untranslated region of the erythropoietin gene (Epo-Tagh), which reduces whole-body erythropoietin expression." (PMID 33443133, 2020). "Much of AHSP’s function was studied in hereditary anemia; it has not been considered in other anemia such as anemia of inflammation/critical illness, which is refractory to erythropoietin administration." (PMID 32629835, 2020).
anemia (continued). "Because most osteosarcoma patients have anemia, which can induce high levels of EPO and TAMs in osteosarcomas express EPOR, verify that EPO plays a role in the protumor function of TAMs, we cultured primary TAMs collected from patients with osteosarcoma lung metastases using CD14 microbeads." (PMID 32908942, 2020). "Erythropoietin (EPO) alteration is the most typical and, certainly, the best detailed example of the potential involvement of derangements of DNA methylation in the pathogenesis of a common CKD complication: anemia." (PMID 32708735, 2020). "Within mild anemia patients, none received a blood transfusion or EPO, 8 received iron and 3 vitamin B12/folic acid." (PMID 32235484, 2020). "Studies have shown that in predialysis patients with non-severe anemia, the early initiation of erythropoietin significantly slows the progression of kidney disease and delays the initiation of renal replacement therapy." (PMID 32154256, 2020). "Unlike anemia of iron deficiency, anemic patients with CKD suffer from various factors such as EPO resistance, functional iron deficiency, and chronic inflammation." (PMID 33178327, 2020). "However, in contrast to HIF2α-mediated EPO production, HIF stabilization in the epithelial cells of the kidney results in suppression of EPO, leading to anemia." (PMID 33143240, 2020). "But in the IRIDA, due to the MT-2 restriction, the EPO/ERFE-mediated hepcidin downregulation in the BMP/SMAD pathway is obstructed, the blocked signal transmission leads both the EPO and the ERFE, and hepcidin simultaneously maintained elevated levels even in the patients with anemia." (PMID 32454791, 2020). "We examined the difference in EPO expression between hypoxemia in 12.9-week-old C57BL mice exposed to a 10% oxygen environment (approximately 82% SpO2) and an anemia group (200 μL of blood removed from the orbital vein for a decrease in the hematocrit from 44% to 33%)." (PMID 32069878, 2020). "Routine clinical tests, including a bone marrow smear, failed to reveal the exact mechanism of the anemia, probably because of our preemptive use of erythropoietin." (PMID 32228698, 2020). "HIF-1α and HIF-2α may play different roles in various anemia conditions; HIF-2α, for example, mediates nucleosome disassembly, in the mechanism of hypoxia-dependent erythropoietin induction." (PMID 32708735, 2020). "In conclusion, JPYS induces the expression of EPO through ERK-mediated HIF-2α protein accumulation and regulates systemic iron recycling, supporting its role in promoting erythropoiesis and improvement of anemia in CKD." (PMID 33178327, 2020). "We predict that supportive treatment with iron and EPO has strong potential in preventing or ameliorating anaemia in these patients but the strongest improvement is due to EPO rather than iron supplementation." (PMID 32451387, 2020). "In patients with chronic kidney disease (CKD), the lack of EPO production by the interstitial tissue of the kidneys results in defective erythropoiesis, which consequently leads to anemia." (PMID 32560029, 2020). "In this context, the finding of a most pronounced EPO effect in patients with no baseline anemia (HR 6.67, 95% CI 1.50–29.73, p < 0.001) is particularly interesting." (PMID 33330669, 2020). "In addition to treating anemia after TBI, EPO has a potential neuroprotective effect acting as biological antioxidant." (PMID 33178833, 2020). "Yet, many premature infants have been treated with EPO for anemia without evident side-effects on brain development." (PMID 32098276, 2020). "Erythropoietin is not licensed in such patients in the UK, but erythropoietin and intravenous iron has been recommended for anaemia in patients before orthopaedic surgery." (PMID 32896294, 2020). "Clinical trials have shown that roxadustat corrected anemia by stimulating the expression of endogenous erythropoietin, which promoted erythropoiesisb and was then non-inferior and superior to placebo and epoetin." (PMID 32850902, 2020).
anemia (continued). "An exploratory subanalysis on the impact of EPO levels on mortality was performed in patients without and with anemia, as well as in patients with normal (CKD 1+2) and moderately impaired renal function (CKD 3)." (PMID 33330669, 2020). "Together, this suggests that modulating EPO levels in serum is not sufficient to treat anemia in CKD patients and that new therapeutic approaches need to be developed." (PMID 33143240, 2020). "Compared to patients with anaemia without CKD, diseased kidneys produce less EPO than would normally be expected relative to the degree of anaemia." (PMID 32665863, 2020). "Many, but not all, MDS patients with anemia have elevated sEPO levels, as EPO production is stimulated by hypoxemia." (PMID 31650290, 2020). "In particular the correlation between hemoglobin and erythropoietin remained negative in populations with high numbers of individuals with normal hemoglobin levels and minimal numbers of significant anaemia." (PMID 31243891, 2019). "Of these, 11,189 patients in the EPO cohort (25.5%) and 487 patients in the non-EPO cohort (1.1%) were administered iron therapy for anemia." (PMID 31484803, 2019). "EPO is required for definitive erythropoiesis and knockout of EPO or EPOR in mice results in death in utero around day 13.5 due to disruption of erythropoiesis in the fetal liver resulting in severe anemia." (PMID 32038269, 2019). "We conclude that physiologically slow-rising serum erythropoietin levels in response to tumor-related or chemotherapy-induced anemia, as opposed to large doses of recombinant erythropoietin, do not increase the pool of breast cancer-initiating cells." (PMID 30700319, 2019). "Erythropoiesis-stimulating agents (ESAs), such as recombinant human erythropoietin (EPO), have been used to treat anaemia in patients with MDS; ESAs constitute an important therapeutic alternative since they reduce transfusion requirements and the risks associated with transfusions." (PMID 31508719, 2019). "Furthermore, treatment of anaemia in MM patients includes red blood cell (RBC) transfusions, recombinant human erythropoietin (rHuEPO) therapy and oral or parenteral iron supplementation." (PMID 31683939, 2019). "However, the use of androgens for the treatment of anemia in CKD patients has been stopped because of inconsistent erythropoietic response, many adverse effects, and the availability of recombinant erythropoietin as a more effective and safer agent." (PMID 31151420, 2019). "It is known that the activation of renin-angiotensin system enhances the erythropoietin productions, while its inhibition due to ACE inhibitors may exacerbate anaemia." (PMID 31521117, 2019). "In fact, mice lacking renal EPO gene expression exhibit severe anemia, although EPO-gene expression is induced in their hepatocytes." (PMID 31798631, 2019). "Alternatively, decreased endothelial and/or cardiomyocyte sensitivity to, rather than too low levels of EPO and/or anemia are important in the progression of HFpEF." (PMID 31551803, 2019). "Since the observed positive stimulating effect of EPO/EPOR on the haematopoiesis, the production of recombinant human EPO (rhEPO) was initiated by pharmaceutical companies and subsequently it was approved for anaemia treatment." (PMID 30606107, 2019). "Regardless of the same degree of anemia, both serum EPO levels and renal EPO mRNA expression at P7 were lower than those at P14." (PMID 29535446, 2018). "Methods and Results: This cross-sectional study enrolled 125 erythropoietin and iron therapy naïve non-dialysis CKD patients, without a identifiable cause of anemia." (PMID 30894885, 2018). "Additionally, bone marrow erythroid hypoplasia is a feature of CRA and circulating erythropoietin (EPO) levels, the main erythrocyte growth factor, are inappropriately low in relation to the degree of anemia and intact renal function." (PMID 30294279, 2018).
anemia (continued). "The reimbursement of erythropoietin stimulating agents (ESA), which is strictly regulated in some countries, may affect the prevalence of anemia." (PMID 29933406, 2018). "Anemia of CKD is mainly normocytic and normochromic, and is primarily due to decreased renal EPO production, reduced RBC survival, and decreased responsiveness to EPO." (PMID 29382128, 2018). "Anemia of chronic kidney disease (CKD) is characterized by a lack of synthesis of erythropoietin leading to reduced red blood cell (RBC) formation and aberrant iron recycling." (PMID 29659573, 2018). "The restoration of EPO production as well as EPOR expression activates EPOR downstream signaling cascades, thereby resulting in the stimulation of erythropoiesis and correction of anemia." (PMID 30108502, 2018). "Preoperative oral or parenteral iron or postoperative parenteral iron with or without erythropoietin-stimulating therapy is useful for the management of perioperative anaemia." (PMID 29375620, 2017). "When asialoEPO, an EPO derivative that does not affect erythropoiesis, is used, anemia is not relieved, but cardiac dysfunction is likewise diminished." (PMID 28850611, 2017). "An appropriate erythropoietic response did not occur to compensate for anaemia during acute cynomolgi malaria despite an increase in erythropoietin levels." (PMID 28938907, 2017). "Improvement of anemia by erythropoietin (ESA) has been accompanied by significant inhibition of the oxidation process, suggesting that anemia itself might aggravate OS." (PMID 29138677, 2017). "Erythropoietin (EPO) promotes proliferation and differentiation of red blood cells and has been used in clinical treatment of anemia, prevention of spinal cord injury, retinal ischemia,skeletal muscle ischemia,pulmonary hypertension, and myocardial ischemia-reperfusion injury." (PMID 28491478, 2017). "Our previous study established extramedullary erythropoiesis in livers without anemia and changes in serum EPO concentrations following the injection of NBP in splenectomized mice." (PMID 27817114, 2017). "It has been treated with erythropoietin in Western countries, and improvement of anemia alleviates profound fatigue, but erythropoietin is not approved for cancer-related anemia in Japan." (PMID 28386794, 2017). "MR16-1 treatment inhibited the decrease of Hb and HCT levels and improved anemia without having an impact on RBC counts or EPO levels in the LC-06-JCK model." (PMID 27068103, 2016). "Treatment with CD133+ cells, but not with PBS or fibroblasts, limited anemia and increased erythropoietin levels both in renal tissue and in circulation." (PMID 27853265, 2016). "Interestingly, amphotericin B-induced anemia has been shown to occur through the inhibition of the transcription factor hypoxia-inducible factor-1 (HIF-1), thereby reducing the expression of erythropoietin (EPO) which controls red blood cell proliferation." (PMID 26433385, 2016). "Strategies used for anemia management were RBV dose reduction [32 patients (15.8%)], EPO [15 (7.4%)], combination of EPO and RBV dose reduction [55 (27%)], EPO and PRBC transfusion [2 (0.9%)], RBV dose reduction and PRBC transfusion [3 (1.5%)] and the three strategies combined [29 (14.2%)]." (PMID 27356107, 2016). "Our latest studies showed that anemia treatment with methoxy polyethylene glycol-epoetin beta (CERA), a long half-life EPO, in CKD patients may inhibit oxidative stress and immune cell apoptosis." (PMID 27034745, 2016). "Low EPO levels in CKD persist after adjustment for eGFR and suggest that the lower EPO response in CKD is not solely correlated with eGFR and that other factors are likely involved that determine the degree of anemia." (PMID 27310832, 2016). "In addition, CD133+ cells promoted the endogenous production of EPO, limiting its transient reduction and mice anaemia after AKI, and contributed to the release of human EPO in the mouse circulation." (PMID 27853265, 2016).